S100A4 (S100 calcium binding protein A4)
Diseases named in the same sentence as S100A4 in open-access papers (continued):
Sharing a sentence is not in itself a finding about the gene and the disease.
neurodegenerative disease (4 papers, 2019 to 2025). A disorder of the central nervous system characterized by gradual and progressive loss of neural tissue and neurologic function. "The top-ranking transcripts ranked by Manhattan distance included CHCHD2 (also known as MNRR1) and Clusterin (CLU) upregulation, with downregulation of FABP3 and S100A4, modulation, all having previously been associated with neurodegenerative disease;." (PMID 41173878, 2025). "Importantly, ferroptosis—a critical component in neuronal cell demise and neurodegenerative diseases—emerges as an intriguing possibility for potential interconnections with C6 S100A4+ SMCs." (PMID 40717095, 2025). "Hence, we analyzed if S100A4 was dysregulated also in an in vivo model of ALS, a neurodegenerative disease where the neuroinflammatory aspect is a well-recognized etiopathogenic mechanism." (PMID 31623154, 2019).
bacterial infection (2 papers, 2024 to 2025). "Upregulation of GJB2, VNN1, DUSP4, SerpinB7, and IL10, and downregulation of PKMYT1, S100A4, GGTA1P, and SLC22A31 were most strongly associated with bacterial infection." (PMID 39395995, 2024). "Despite these findings, the function of S100a4 in response to bacterial infections in the testis was not completely understood." (PMID 41031892, 2025).
benign tumors (2 papers, 2005 to 2020). "In the rodent model systems, elevated levels of S100A4 can only synergise with growth-promoting oncogenic products such as c-erbB-2/neu or have to be expressed in benign tumours before metastasis can be induced." (PMID 16265347, 2005). "A six-biomarker model including HE4, CA125, CEACAM1, CTSV, CXCL6, S100A4 and age was found to be the best model for discriminating between benign tumors and EOC with AUC 0.921 (0.863–0.979), sensitivity 0.897 / specificity 0.889 at best point cut-off (p = 0.025)." (PMID 33075095, 2020).
brain disease (2 papers, 2016 to 2018). "Thus, the S100A4-induced ErbB4 modulation may potentially play a role in many brain disorders, holding promise for future therapeutic applications." (PMID 30083275, 2018).
cardiovascular diseases (2 papers, 2019 to 2024). "Thus, S100A4 could be involved in the comorbidity of RA such as cardiovascular diseases." (PMID 31037071, 2019).
neurological diseases (2 papers, 2021 to 2022). "This review aims to summarize the role of S100A4 in different physiological and pathological conditions of the nervous system and highlight S100A4 as a common factor involved in the pathogenesis of neurological diseases." (PMID 33918416, 2021). "The role of S100A4 in both controlling neuron survival and axonal elongation, as well as in the recruitment of inflammatory cells, was observed in neurological disorders such as brain trauma and excitotoxic damage as occurring in epilepsy." (PMID 33918416, 2021). "Interestingly, besides exerting neuroprotective actions, S100A4 is involved in the inflammatory machinery that could contribute to the pathogenesis of nervous system disorders." (PMID 33918416, 2021). "Nonetheless, S100A4 inhibitors, particularly by reducing glial hyperactivation following acute or chronic damage, could be used to ameliorate neuroinflammatory mechanisms in neurological diseases." (PMID 33918416, 2021). "Altogether, these findings strongly suggest that S100A4 modulation can affect the mechanisms involved in nervous system disorders, and we therefore believe that the investigation of S100A4-related drugs in pre-clinical and clinical trials could be attractive to the field of neurobiology." (PMID 33918416, 2021).
cardiac disease (1 paper, 2018). "Only few members of the family have been linked to cardiac disease, among which are S100A1 and S100A4." (PMID 30283351, 2018). "In summary, much evidence points toward an emerging role of S100A4 in cardiac disease, albeit it is not yet clear whether S100A4 exerts a detrimental or beneficial function." (PMID 30283351, 2018).
inflammatory myopathy (1 paper, 2014). "Thus, we can speculate that circulating S100A4 protein may reflect the global disease activity, including extramuscular organ involvement, rather than functional muscle impairment in inflammatory myopathy." (PMID 25359220, 2014).
S100A4 also shares sentences with these, for which no sentence is quoted: idiopathic pulmonary fibrosis (13 papers); idiopathic inflammatory myopathies (3); acute myocardial infarction (2); fatty liver disease (2); fibrosarcoma (2); frontotemporal dementia (2); Hyperkeratosis (2); kidney (2); Lewy body disease (2); lung squamous cell carcinoma (2); myocardial ischemia (2); Peritoneal Fibrosis (2); acute leukemia (1); acute lymphoblastic leukaemia (1); alcoholic cirrhosis (1); alcoholic liver diseases (1); anaphylaxis (1); anemia (1); ankylosing spondylitis (1); anxiety disorder (1); aortic aneurysm (1); aortic stenosis (1); astrocytoma (1); B cell lymphomas (1); benign breast tumour (1); benign prostate hyperplasia (1); Bovine mastitis (1); brain glioblastoma (1); calcification (1); calcinosis (1).
A further 69 diseases each share a sentence with S100A4 in 1 paper.